HMGB1 (high mobility group box 1)
Diseases named in the same sentence as HMGB1 in open-access papers (continued):
Sharing a sentence is not in itself a finding about the gene and the disease.
Sepsis (continued). "Antagonism of cerebral HMGB1 improved the proliferation and IL-2 release of T cells and reversed the polarization of Th2 cells in the sepsis 48 h group." (PMID 34512319, 2021). "From the clinical results, we propose that serum HMGB1 + EVs in sepsis patients can be used as a marker for sepsis diagnosis." (PMID 34743181, 2021). "Accordingly, we have generated polyclonal and monoclonal antibodies against human HMGB1 and tested their efficacy in animal models of lethal endotoxemia and sepsis induced by a surgical procedure termed cecal ligation and puncture (CLP)." (PMID 34571869, 2021). "High Mobility Group Box 1 protein (HMGB1) is a major alarmin which is passively released from injured or necrotic cells in sepsis." (PMID 33842398, 2021). "During sepsis, the drop in pH and zinc concentration of the blood leads to disruption of HMGB1’s binding with sialic acid, enabling the free HMGB1 to bind with TLRs and RAGE present on immune cells and the endothelium." (PMID 33658363, 2021). "AE impaired HMGB1 release via decreasing lactate and Glut1 expression and increasing insulin expression during sepsis." (PMID 34493741, 2021). "Studies have recently demonstrated that increasing the level of cellular HMGB1 promotes pyroptosis and apoptosis to mediate organ injury in sepsis." (PMID 34747306, 2021). "In general, sepsis has been studied in animal models and adults, while there are limited data on the pediatric population; thus, more research is needed to determine the role of HMGB1 in sepsis." (PMID 33140586, 2021). "We found that circTLK1 upregulated HMGB1 expression by sponging miR-106a-5p in the HK-2 cells, and miR-106a-5p and HMGB1 were involved in circTLK1-mediated sepsis-induced AKI in the cells." (PMID 34250012, 2021). "High mobility group protein B1 (HMGB1) is an important late inflammatory factor and an endogenous danger signal in the pathological process of sepsis." (PMID 34531754, 2021). "HMGB1 was involved in the development of the inflammatory response and was a promising therapeutic target for sepsis treatment." (PMID 34493741, 2021). "HMGB1 mediates splenomegaly and expansion of splenic CD11b+ly-6C(high) inflammatory monocytes in murine sepsis survivors." (PMID 33925132, 2021). "In genetic depletion of genes encoding for Pink and Park2, a subsequent decrease in neurotransmitter dopamine was accompanied with increase of late sepsis mediator—HMGB1, via mechanism of HIF-1α-dependent anaerobic glycolysis and NLRP3 inflammasome activation." (PMID 34824200, 2021). "In the later stages of sepsis, hepatocytes and other somatic cells actively release HMGB1 in very high concentrations." (PMID 34152806, 2021). "Several observations have indicated that enhance expression of HMGB1 contributed to cardiac dysfunction during sepsis." (PMID 34410682, 2021). "This fast appearance contradicts the proposition of HMGB1 as the late mediator of sepsis inducing prenatal lethality in mice." (PMID 34439812, 2021). "AE decreased the serum levels of lactate and HMGB1 but increased blood glucose levels and serum insulin levels during sepsis." (PMID 34493741, 2021). "It was previously reported that SIRT1-modulated HMGB1 deacetylation inhibited acute kidney injury incurred by sepsis." (PMID 34906140, 2021). "Lidocaine has also been shown in vivo (in animal models of sepsis and sterile inflammation) to inhibit expression of the inflammatory mediator high mobility group box 1 (HMGB1), which in turn suppresses activation of NF-κB." (PMID 34408981, 2021). "HMGB1 participates in sepsis and sterile inflammation, and creates a bridge between these detrimental reactions if its release is exaggerated." (PMID 34439812, 2021). "Other complimentary work has shown that an anti-HMGB1 neutralizing monoclonal antibody (mAb) prevented death due to sepsis and acute liver injury and inhibited HMGB1 endocytosis." (PMID 34684184, 2021).
Sepsis (continued). "We previously showed that over-activation of caspase-11 is driven by hepatocyte-released high mobility group box 1 (HMGB1), which delivers extracellular LPS into the cytosol of host cells during sepsis." (PMID 33854044, 2021). "Here, we found that the serum-derived EVs of sepsis patients and macrophages contain high levels of HMGB1 and stimulate the activation of the NLRP3 inflammasome and liver damage." (PMID 34743181, 2021). "HMGB1 knockout models in mice also proved that platelet-derived HMGB1 is a key player in mediating thrombosis during sepsis." (PMID 34235204, 2021). "In a CLP model of sepsis, mice treated with anti-HMGB1 antibody had a significantly lower mortality than mice undergoing CLP alone." (PMID 33732235, 2021). "During sepsis or sterile tissue injury, the nuclear protein high mobility group box 1 (HMGB1) can be released to the extracellular space and ultimately into systemic circulation, where it mediates systemic inflammation and remote organ failure." (PMID 34107884, 2021). "Consistently, the blockade of extracellular HMGB1 activities with neutralizing antibodies even during a late stage of sepsis still restored neutrophil NADPH activity and anti-bacterial capacities." (PMID 34571869, 2021). "To further develop this model, we introduced HMGB1, a DAMP (17, –19) associated with poor prognosis in late sepsis." (PMID 33658363, 2021). "Since the discovery of HMGB1 as a late‐stage inflammatory mediator of sepsis, the role of HMGB1 in childhood sepsis has also received considerable attention." (PMID 33140586, 2021). "For example, HMGB1 contributes to anti-inflammatory mechanisms during sepsis by forming a complex with the acute phase protein haptoglobin." (PMID 34685561, 2021). "Increased release of HMGB1 is considered with critical involvement in the severity of sepsis, and inhibition of HMGB1 significantly ameliorates multiple organ injury and improves the survival of septic animals." (PMID 34512319, 2021). "The results of this study showed that gut-origin sepsis was associated with increased expression of the proinflammatory cytokines (TNF-α, IL-1β, IL-6, and HMGB1) and decreased expression of anti-inflammatory cytokine IL-10." (PMID 34790828, 2021). "The results of previous studies on the relationship between plasma HMGB1 and sepsis mortality are contradictory." (PMID 33947887, 2021). "Circulating levels of high mobility group box 1 (HMGB1) are increased as a late component of the systemic inflammatory response and have been implicated in sepsis-associated mortality." (PMID 34073678, 2021). "HMGB1, a danger-associated molecular pattern (DAMP) previously associated with sepsis and shown to activate TLR4 signaling, was released into serum within minutes after the burn, resulting in an increase in TLR4-mediated proinflammatory signaling." (PMID 34152806, 2021). "Disparity in proportion of specific subtypes of sepsis patients among previous studies and ours have resulted in conflicting significance of HMGB1 in mortality prediction." (PMID 33947887, 2021). "Silencing HMGB1 in a mouse model of sepsis mitigated the cytokine storm of DCs and macrophages, as well as reduced lymphocyte apoptosis and mortality." (PMID 33925132, 2021). "It was well documented that HMGB1 was involved in the development of sepsis and was a promising therapeutic target for sepsis treatment." (PMID 34493741, 2021). "We included extracellular DNA, histones, and HMGB-1 in our analysis, as they represent well-characterized DAMPs whose release is critical in sepsis." (PMID 33790693, 2021). "Though reduction of oxidized HMGB1 by thioredoxin is sufficient to maintain the reduced form, such reaction is low in efficiency during sepsis." (PMID 34824200, 2021). "Contents of brain HMGB1, including cortex and hippocampus, were significant increased after the induction of sepsis." (PMID 34512319, 2021).
Sepsis (continued). "HMGB1, commonly regarded as a later lethal mediator in sepsis, is significantly increased in different brain regions under expose to sepsis." (PMID 31924221, 2020). "Taken together, these results suggested that toddalolactone protects LPS-induced sepsis and attenuates LPS-induced inflammatory response by modulating HMGB1-NF-κB translocation." (PMID 32153412, 2020). "Elevated circulating HMGB1 is associated with inflammation in hemolytic disorders including SCD and sepsis, suggesting a shared inflammatory signaling pathway through TLR4/Bruton tyrosine kinase for both heme and HMGB1 in SCD." (PMID 33584641, 2020). "A recent study reports that haptoglobin, an acute phase extracellular hemoglobin-binding protein, binds circulating HMGB1 and thereby protects against sepsis." (PMID 33391251, 2020). "Compared with other early -phase pro-inflammatory contents, for instance tumor necrosis factor (TNF) and IL-1β, HMGB1 began to appear 8 h and significantly increased after initiation of sepsis." (PMID 33552058, 2020). "In this review, we mainly introduce the relevant pathways of HMGB1 in mediating inflammation in sepsis." (PMID 33552058, 2020). "Extracellular release of HMGB1 in disease pathogenesis, such as sepsis, arthritis, colitis, and ischemia reperfusion, has validated that the inhibition of HMGB1 significantly reduces the severity of many of these conditions." (PMID 32019145, 2020). "Administration of HMGB1-neutralizing agents also provides significant protection in animal models of experimental sepsis, drug-induced liver injury, ischemia reperfusion injury and trauma." (PMID 33391251, 2020). "In sepsis, the role of CQ in cell death reduction has been demonstrated, preventing the release of HMGB1." (PMID 32724296, 2020). "HMGB-1 contributes to the increases in gut permeability in sepsis including increase in translocation of bacteria." (PMID 33584688, 2020). "While TNF-α and IL-1 are released early by the macrophages in inflammation, HMGB-1 is a late mediator in sepsis." (PMID 33584688, 2020). "Emerging evidence confirms the excessive activation of HMGB1/RAGE signaling in sepsis models and in patients with sepsis." (PMID 32089649, 2020). "Similar effects of sulfatide were also confirmed in the LPS-mediated murine experimental sepsis model, showing decreased levels of serum HMGB1, increased survivability, and reduced pathological severity." (PMID 32655573, 2020). "In both experimental sepsis models and in sepsis patients, the levels of HMGB1 in circulation are remarkably increased, and the concentration of circulating HMGB1 is positively correlated with the severity of inflammation and disease." (PMID 33552058, 2020). "The disease implications relate to the recently discovered central roles of hepatocyte-derived HMGB1 to sepsis pathogenesis and inflammatory diseases of the liver." (PMID 32328059, 2020). "For example, HMGB1 has been postulated to play a role in the pathogenesis of inflammatory diseases such as sepsis and rheumatoid arthritis." (PMID 33126860, 2020). "Administration of recombinant HMGB1 to mice recapitulates many clinical signs of sepsis, including fever, derangement of intestinal barrier function, lung injury, and lethal multiple organ failure." (PMID 32629817, 2020). "The high-mobility group box 1 (HMGB1) is secreted by platelets and up-regulated under abnormal coagulation, sepsis, disseminated intravascular coagulation as well as trauma." (PMID 32874136, 2020). "HMGB1 can also induce inflammatory anemia and cognitive impairment, which is considered to be related to neuroinflammation, among sepsis survivors." (PMID 33552058, 2020). "In sepsis, extracellular HMGB1 is known to be released in its reduced form; it is considered a potent pro-inflammatory cytokine and a promising therapeutic target in clinical studies." (PMID 32655573, 2020).
Sepsis (continued). "For example, during an infection, the high-mobility group box 1 (HMGB1), which belongs to the alarmin family, is released into the extracellular space and participates in the pathogenesis of sepsis." (PMID 33425215, 2020). "Extracellular HMGB1, a potent pro-inflammatory mediator, can initiate an inflammatory response, facilitating the progression of sepsis and ALI." (PMID 32600307, 2020). "So far, the role of HMGB1 has been established in inflammatory processes of conditions, such as arthritis, hepatitis, sepsis, rheumatoid arthritis, and systemic lupus erythematosus, as well as the pathogenesis of atherosclerosis and cancer." (PMID 32796569, 2020). "It was reported that the expression of HMGB1 protein was suppressed by α7nAChR agonist nicotine and the survival of post-sepsis acute lung injury was improved." (PMID 33193374, 2020). "Our findings and the findings of others established that active release of HMGB1 by hepatocytes is the dominant source of systemic levels of HMGB1 during endotoxemia and sepsis." (PMID 32328059, 2020). "To further investigate the molecular mechanism underlying the regulatory roles of sesamin in the inflammatory effects on sepsis, we used RT-qPCR and Western blotting to evaluate the HMGB1/TLR-4/IL-33 signalling pathway." (PMID 32893702, 2020). "We focused on glycyrrhizin and chloroquine as they show strong activity in blocking extracellular HMGB1 function under various inflammatory conditions, including experimental models of sepsis and septic shock." (PMID 33313438, 2020). "With many animal model studies already establishing a clear link in sepsis attenuation by HMGB1 inhibition, it is now time to assess if these findings can translate on to human models." (PMID 32629817, 2020). "This area of investigation is important because active HMGB1 release by hepatocytes has been shown to be critical in the pathogenesis of not only sepsis lethality but also many liver-based diseases." (PMID 32328059, 2020). "This review mainly discusses current perspectives on the roles of HMGB1 in sepsis-related inflammation and immunosuppressive process and its related internal regulatory mechanisms." (PMID 33552058, 2020). "The progression from acute respiratory failure to sepsis has been correlated with the release of high-mobility group box 1 protein (HMGB1)." (PMID 32629817, 2020). "HMGB1, as a late lethal inflammatory mediator, is reported to play an important role in sepsis outcomes." (PMID 32957908, 2020). "Thence, exploring the role between HMGB1 and MDSCs is of great significance in discovering new sepsis-related immunotherapy strategies." (PMID 33552058, 2020). "A high concentration of HMGB1 in the plasma of patients with severe sepsis correlates with a poor prognosis and high mortality, and the pharmacologic inhibition of HMGB1 improved survival in animal models of acute inflammation and severe sepsis." (PMID 32498020, 2020). "The pathophysiological mechanism is highly related to an important late-acting cytokine high mobility group box-1 protein (HMGB1), which is increased markedly in sepsis and plays an important role in provoking inflammation and immune responses." (PMID 32071292, 2020). "High level of HMGB1 acts as a specific role in the development of immunosuppression during late phase of sepsis." (PMID 33552058, 2020). "Green tea leaf (Camellia sinensis folium) extract also reduces endotoxin-induced release of HMGB1 and is therefore proposed to possess the ability to decrease mortality from sepsis if taken regularly." (PMID 32629817, 2020). "In both mice subjected to sepsis and patients surviving septic shock, HMGB1 decreased the capacity of neutrophil to kill bacteria through mediating neutrophil nicotinamide adenine dinucleotide phosphate (NADPH) oxidase dysfunction." (PMID 33552058, 2020). "High mobility group box-1 protein (HMGB1) is a critical mediator of lethal sepsis, which has prompted investigation for the development of new treatment for inflammation." (PMID 33603756, 2020).
Sepsis (continued). "The anti-HMGB1 antibody is one of the most powerful HMGB1 inhibitors and has been used in many inflammatory disease models such as sepsis and brain infarction." (PMID 32760399, 2020). "HMGB1, as a downstream mediator of sepsis, has been previously demonstrated by its regulatory role in inflammatory response and apoptosis, which is closely associated with different organ injuries." (PMID 32412059, 2020). "A previous study also reported that blood HMGB1 levels were unchanged and remained at an elevated level in patients with sepsis." (PMID 32635454, 2020). "The effect and mechanism of salidroside on sepsis-induced acute lung injury is mediated by the inhibition of inflammatory responses and HMGB1 production in bacterial LPS-treated macrophages and mice." (PMID 32629817, 2020). "In animal experiments, it was demonstrated that inhibition of extracellular HmgB1 attenuates inflammation and increase the organism defenses against several diseases (including sepsis, diabetes, ischemia, and damage to the heart and liver)." (PMID 33114717, 2020). "Several studies showed that post-sepsis syndrome also includes immune function impairments such as a persistent inflammatory state characterized by an increase in High mobility group box 1 (HMGB1) levels in plasma after sepsis." (PMID 33658992, 2020). "Traditionally used to treat cardiovascular disorders, it was shown to be protective against lethal LPS-induced endotoxemia and sepsis by decreasing HMGB1 levels in vivo in a murine model." (PMID 32629817, 2020). "HMGB1 contributes to lethality in sepsis by delivering extracellular LPS to cytosolic caspase-11 in macrophages and endothelial cells." (PMID 32328059, 2020). "Inhibition of Caspase-11 activation leads to less IL-1α and HMGB1 release in the peritoneal cavity, and it reduces abdominal inflammation during sepsis." (PMID 33055424, 2020). "The HMGB1 mRNA levels were also upregulated in tissues from mice with CLP-induced sepsis, which was significantly reversed by treatment with STAT3 decoy ODNs." (PMID 32943679, 2020). "Other improvements of cognitive impairment after sepsis have been achieved with some of the treatments known to protect mice against sepsis‐induced death, such as anti‐HMGB‐1 antibodies or electroacupuncture." (PMID 32176432, 2020). "In conclusion, our study showed the effect of sulfatide in suppressing the secretion of HMGB1 under LPS stimulation, and its potential as anti-sepsis treatment." (PMID 32655573, 2020). "Ghrelin also reduces bacterial load in sepsis, which also indirectly contributes to less HMGB1 secretion." (PMID 33584688, 2020). "These contradictory results indicate that the functions of HMGB1 in sepsis are complex and different." (PMID 33552058, 2020). "This is similar to effects we have seen in other model systems (e.g. sepsis) where hepatocyte-derived HMGB1 is the main source of HMGB1 and drives inflammatory responses and also can induce inflammatory cell death." (PMID 33238880, 2020). "HMGB1 facilitates LPS entering cells to trigger pyroptosis, which plays an important role in sepsis." (PMID 32983116, 2020). "Other research on sepsis model also indicated that hepatocyte-derived HMGB1 transported LPS into the cytosol of macrophages and endothelial cells, via RAGE-mediated internalization." (PMID 33552058, 2020). "Neutrophil dysfunction mediated by HMGB1 is also an aspect of the immunosuppressive mechanism of sepsis." (PMID 33552058, 2020). "We further focused on the response of ERS in DCs to explore the precise mechanisms underlying cytoprotective actions of SESN2 against apoptosis induced by HMGB1 or during sepsis." (PMID 32071292, 2020). "HMGB1 promotes sepsis-induced organ dysfunction through suppressing neutrophil ability to clear bacteria, and so enhancing persistent inflammation." (PMID 33552058, 2020). "This demonstration of an intimate relationship between HRG and HMGB1 provides direct supporting evidence for the supplementary treatment of sepsis with HRG." (PMID 32498020, 2020).